SAMHD1 (SAM and HD domain containing deoxynucleoside triphosphate triphosphohydrolase 1)
Diseases named in the same sentence as SAMHD1 in open-access papers (continued):
Sharing a sentence is not in itself a finding about the gene and the disease.
acute myeloid leukemia (16 papers, 2018 to 2025). Acute myeloid leukemia (AML) is a group of neoplasms arising from precursor cells committed to the myeloid cell-line differentiation. "Conversely, high SAMHD1 expression in acute myelogenous leukaemia patients is associated with efficacy reduction of the nucleoside-analogue anti-cancer drugs Cytarabine and Clofarabine32–34 as a result of SAMHD1 hydrolysis of their triphosphorylated forms." (PMID 32576829, 2020). "For cladribine, SAMHD1 involved in proliferation of acute myeloid leukemia cells and PCM1 involved in gene fusions in atypical chronic myeloid leukemia were found." (PMID 41146244, 2025). "Targeting SAMHD1’s ara-CTPase activity has recently been demonstrated to enhance ara-C efficacy in acute myeloid leukemia." (PMID 38237141, 2024). "Recently, high levels of SAMHD1 in myeloid blasts were found to correlate with low sensitivity to cytarabine in acute myeloid leukemia." (PMID 34738194, 2022). "High SAMHD1 levels indicate poor clinical response to nucleoside analogues such as cytarabine, decitabine, and nelarabine in acute myeloid leukaemia (AML), acute lymphoblastic leukaemia, and Hodgkin lymphoma." (PMID 34641952, 2021). "SAMHD1 limits the efficacy of cytarabine by detoxifying cancer cells of its active metabolite, resulting in worse survival for acute myeloid leukaemia patients." (PMID 31950591, 2020). "SAMHD1 has a deoxyribonucleoside (dNTP) triphosphohydrolase activity essential for clinical response to dNTP analog therapeutic agents, including cytarabine and decitabine in acute myeloid leukemia (AML)." (PMID 38406263, 2024). "Owing to its dNTPase activity, SAMHD1 can degrade the analog cytarabine triphosphate and reduce its concentrations in cells, such as the patient-derived acute myeloid leukemia blasts, thereby posing a significant barrier to the effective analog cytarabine-based treatment." (PMID 35978833, 2022). "SAMHD1 is a deoxynucleoside triphosphate triphosphohydrolase (dNTPase) that restricts viral replication in infected cells and limits the sensitivity to cytarabine by hydrolysing its active metabolite, as recently shown in acute myeloid leukemia." (PMID 34738194, 2022). "SAMHD1 reduces cytarabine (Ara-C) toxicity in acute myeloid leukemia cells." (PMID 29352181, 2018). "Since SAMHD1 limits the efficacy of cytarabine by hydrolyzing the active metabolite, Ara-CTP, it could be hypothesized that cases with high frequency of SAMHD1 expressing cells are less sensitive to this essential therapeutic component, similar to findings in acute myeloid leukemia." (PMID 34738194, 2022). "Finally, it was reported that SAMHD1, which also hydrolyzes ara-CTP, is a marker for the ara-C treatment of acute myeloid leukemia patients." (PMID 37567474, 2023). "Our aim was to investigate whether SAMHD1 protein expression correlates to progression free survival in MCL, in a similar manner as it does in acute myeloid leukemia." (PMID 34738194, 2022). "However, for patients with acute myeloid leukemia it was observed that Ara-CTP, the active metabolite of cytarabine, is a direct substrate of SAMHD1." (PMID 29352181, 2018).
Autoimmunity (16 papers, 2013 to 2026). The occurrence of an immune reaction against the organism's own cells or tissues. "SAM domain-containing proteins are implicated in normal and pathologic mechanisms, including SAMHD1 in autoimmunity and SAMD9/SAMD9L in myelodysplasia and myeloid malignancies." (PMID 32241909, 2020). "Recently, SAMHD1 was implicated in the DNA damage response and in preventing autoimmunity by maintaining genome integrity." (PMID 29311560, 2018). "Mutations in SAMHD1 are associated with Aicardi–Goutières syndrome (AGS)—an autoimmune disorder characterized by a progressive inflammatory encephalopathy, spontaneous type I IFN production in the cerebrospinal fluid, and upregulated IFN-stimulated gene (ISG) expression." (PMID 33801276, 2021). "Mutations in SAMHD1 are thought to account for around 13% of AGS mutations and have been linked to several other interferonopathies—demonstrating a clear link between SAMHD1 dysfunction and autoimmunity." (PMID 33519829, 2020). "Mutations in SAMHD1 result in increased dNTP pools in fibroblasts from AGS patients, suggesting that the dNTPase function of SAMHD1 prevents autoimmunity by maintaining genome stability." (PMID 26416562, 2015). "To characterize the role of SAMHD1 in the onset of autoimmunity and viral restriction in vivo, we and others generated SAMHD1 knockout mice (SAMHD1 KO)." (PMID 26667483, 2015). "Besides its protective role in autoimmunity, SAMHD1 was also shown to suppress the antiviral immune response upon infection." (PMID 33801276, 2021). "With regard to the phospho-specific regulation of SAMHD1, it will be of high interest to determine in which cells SAMHD1 is keeping L1 in check and how this is connected to the role of SAMHD1 in preventing autoimmunity, cancer development, and maintaining genome integrity." (PMID 29610582, 2018). "A function of SAMHD1 in suppressing reverse transcription of endogenous retroviruses and retrotransposons may explain the role of SAMHD1 in cancer and autoimmunity." (PMID 24854580, 2014). "In contrast to Trex1−/− and Adar1−/− mice, SAMHD1-deficient mice did not develop detectable pathology or autoimmunity." (PMID 23972988, 2013). "SAMHD1-deficient mice do not develop any detectable pathology or autoimmunity." (PMID 34332594, 2021). "However, the upregulation of IFNs and ISG products in SAMHD1 KO mice was undetectable in most tissues and did not cause the mice to develop neurological impairments or autoimmunity." (PMID 32244340, 2020). "The studies performed in the SAMHD1 KO mice suggests that the loss of mSAMHD1 alone does not induce an equivalent IFN response to what is seen in AGS patients or allow the development of detectable autoimmunity." (PMID 32244340, 2020). "Neither SAMHD1-deficient mouse strain developed detectable pathology or autoimmunity, suggesting that mSAMHD1 function might be redundant or not directly involved in the innate immune responses to nucleic acids in mice." (PMID 24257155, 2013). "In this study, we explored the role of SAMHD1 in regulating nucleic acid-mediated type I IFN signaling to understand the molecular pathogenesis of AGS and overlapping autoimmune disorders." (PMID 29311560, 2018). "The finding that the phosphorylation of SAMHD1 at T592 regulates its activity against retroelements but not necessarily intracellular dNTP level suggests that the dNTP hydrolase activity might not be the only function of SAMHD1 important for its antiviral activity and for controlling autoimmunity." (PMID 29610582, 2018).
breast carcinoma (12 papers, 2015 to 2024). "In the UKBiobank, the vast majority (99.4%) of individuals possessing SAMHD1 mutations were heterozygote carriers, who had a twofold increased risk of breast cancer." (PMID 35023831, 2022). "SAMHD1 associations with cancer appear to be driven by increased risk for multiple site-specific cancers, notably prostate cancer in men, mesothelioma in both men and women, and suggestive evidence for higher breast cancer susceptibility in women." (PMID 39261734, 2024). "First, heterozygous SAMHD1 mutations may be an overlooked risk factor for breast cancer considering that ~1 in 130 UKBiobank participants possessed a genetic mutation conferring twofold elevated risk." (PMID 35023831, 2022). "Indeed, our finding that SAMHD1 mutations associate with both elevated mtDNA-CN levels and risk of breast cancer belies the prevailing notion that higher mtDNA-CN is always a protective signature of proper MT function and healthy cells." (PMID 35023831, 2022). "Whole-transcriptomic profiling of SAMHD1-depleted tumors identified downregulation of IL-12 signaling pathway as the molecular mechanism determining breast cancer prognosis." (PMID 37667113, 2024). "SAMHD1 expression was evaluated in a clinical cohort of early breast cancer patients with stage II-III treated with NACT." (PMID 37667113, 2024). "SAMHD1 expression was associated to increased risk of recurrence and higher Ki67 levels in post-NACT tumor biopsies of breast cancer patients with residual disease." (PMID 37667113, 2024). "SAMHD1 expression is a novel prognostic biomarker in early breast cancer that impacts immune-mediated signaling and differentially regulates inflammatory intra-tumoral response." (PMID 37667113, 2024). "Overall, our clinical data suggest that SAMHD1 expression is a relevant prognostic factor in breast cancer in the neoadjuvant setting." (PMID 37667113, 2024). "To investigate the signalling pathways affected by SAMHD1 depletion, we took advantage of SAMHD1-KO breast cancer cell lines, previously developed in our group, to perform a whole transcriptome profiling." (PMID 36845138, 2023). "We have previously shown that SAMHD1 knockout breast cancer cells presented increased DNA damage and apoptosis, an effect that was enhanced upon platinum-based treatment." (PMID 36845138, 2023). "To identify pathways specifically affected by the downregulation of SAMHD1 in breast cancer cells, we performed gene-set enrichment analysis (GSEA) using the Reactome gene-sets." (PMID 36845138, 2023). "For breast cancer patients, SAMHD1 positivity was correlated with high grade breast tumors (p = 0.017)." (PMID 35158911, 2022). "SAMHD1 somatic mutations have been identified in several human cancers, including chronic lymphocytic leukemia (CLL), myeloma, breast cancer, lung carcinoma, colon and rectal cancer, pancreatic cancer, and glioblastoma." (PMID 26416562, 2015). "Taken together, our results indicate that SAMHD1 expression exerts a pro-tumorigenic effect in breast cancer, through a process that involves the interaction between tumors cells and TME putatively through the differential regulation of inflammatory intratumoral response." (PMID 37667113, 2024). "Additionally, it would be of great interest in further studies of breast cancer samples to discriminate between different subtypes and correlate whether differing SAMHD1 expression has an impact on disease prognosis." (PMID 34480199, 2022). "Exclusion of breast cancer cases was attenuated but did not nullify the association with ‘cancer (suspected or other)’ (OR = 1.36; 95% CI, 1.10–1.67; p=0.004) suggesting that SAMHD1 mutations may also increase risk of other cancers, as has been shown for colon cancer." (PMID 35023831, 2022). "We used virus-like particles (VLPs) containing Vpx to deplete SAMHD1 in the cervical cancer cell line HeLa and the breast cancer cell line MDA-MB231, which both express SAMHD1." (PMID 32402273, 2020).
breast carcinoma (continued). "SAMHD1 expression is also significantly lower in other cancers, including cutaneous T-cell lymphoma (CTCL), lung carcinoma, breast carcinomas and various tumor cell lines." (PMID 26416562, 2015). "Interestingly, SAMHD1 positivity was associated with grade III tumors (p = 0.025), higher levels of Ki67 after NACT (p = 0.017) and increased risk of recurrence (p = 0.005), suggesting that SAMHD1 expression might represent a relevant prognostic biomarker for breast cancer post-NACT." (PMID 37667113, 2024). "Survival analysis showed that SAMHD1-expressing tumors presented shorter time-to-progression and overall survival than SAMHD1 negative cases, suggesting that SAMHD1 expression is a relevant prognostic factor in breast cancer." (PMID 37667113, 2024). "SAMHD1 expression varied significantly across tumor types, ranging from high percentage of positivity in rectal to low expression in pancreatic tumors, whereas values of 50–60% positivity were obtained for ovarian, NSCLC and breast cancer cases." (PMID 35158911, 2022). "Thus, we determined the value of SAMHD1 as a predictive factor in ovarian, NSCLC and breast cancer treated with corresponding antimetabolite-containing regimens." (PMID 35158911, 2022). "NR1H3 is a nuclear receptor component and an anti-invasive gene for bladder cancer; PARP12 has been reported to suppress hepatocellular carcinoma metastasis; SAMHD1 is yet another suppressor of epithelial transformation; PSMB9 is a key metastasis suppressor for breast cancer." (PMID 33562461, 2021). "However, a positive correlation between SAMHD1 and TCP1 expression was identified (p = 0.0081), confirming the transcriptomic data and pointing towards TCP1 as an additional factor determining SAMHD1 effect in breast cancer." (PMID 37667113, 2024). "Finally, the median OSCD for SAMHD1 negative breast cancer patients was 116.7 months in front of 65.9 months for SAMHD1 positive (log rank function, p = 0.004)." (PMID 35158911, 2022). "Indeed, data derived from TCGA or ICGC databases show similar results, pointing towards SAMHD1 tumor promoter function in ovarian carcinoma, but not in lung and breast carcinoma, in contrast with the data presented here." (PMID 35158911, 2022). "A first analysis of primary breast cancer samples indicated that SAMHD1 protein expression might be reduced or even absent in approximately 50% of cases." (PMID 34480199, 2022). "From our data, we cannot rule out the possibility that synergy observed in breast cancer cell lines might be not entirely dependent on SAMHD1, but due to a combination of different factors that deserve further investigation." (PMID 32197329, 2020). "In breast cancer patients, median DFS was 64 months for SAMHD1 negative patients compared to 21 months for SAMHD1 positive patients (p = 0.001)." (PMID 35158911, 2022).
colon cancer (12 papers, 2020 to 2024). "Chronic lymphocytic leukaemia (CLL), T‐cell prolymphocytic leukaemia, colon cancer and mantle cell lymphoma, amongst others, have all had SAMHD1 mutations identified within." (PMID 35583750, 2022). "For example, the accumulation of dNTPs in colon cancers with heterozygous SAMHD1 mutations exacerbate MMR mutation phenotypes." (PMID 34696158, 2021). "Frequently mutated SAMHD1 found in colon cancers was suggested to be involved in tumorigenesis with defective mismatch repair (MMR) and also act as a resistance factor for anticancer drugs." (PMID 32983988, 2020). "We speculated that a higher rate of mutations may occur in patients with high expression of SAMHD1 resulting in disease progression because mutations in SAMHD1 that alter its dNTPase activity are associated with colon cancer." (PMID 35978833, 2022). "In contrast, stable overexpression Flag-SAMHD1 in shSAMHD1 colon cancer cells increases the survival rate in a cisplatin and doxorubicin concentration-dependent manner, respectively." (PMID 37081042, 2023). "Co-occurrence of SAMHD1 mutations with mutations in genes encoding mismatch repair (MMR) components, a major pathway in maintaining DNA replication fidelity, has been observed in colon cancer." (PMID 39206868, 2024). "In addition, stably expressing Flag-SAMHD1 in shSAMHD1 colon cancer cells significantly decreased cleaved-PARP, cleaved-Caspase 3 and γH2AX when compared to Flag vector." (PMID 37081042, 2023).
colorectal cancer (11 papers, 2013 to 2025). A primary or metastatic malignant neoplasm that affects the colon or rectum. "Furthermore, analyses of The Cancer Genome Atlas (TCGA) database indicated that downregulation of SAMHD1 expression occurs in various cancer types and is associated with poor survival in colorectal cancer patients." (PMID 33857133, 2021). "In the colorectal cancer, high expression SAMHD1 correlated with metastasis and indicated poor prognosis of stage II patients." (PMID 36578072, 2022). "Using subgroup analysis involving retrospective patient cohorts, we evaluated the association between the SAMHD1 biomarker and the benefits from adjuvant chemotherapy and survival in patients with stage II and III colorectal cancer." (PMID 35978833, 2022). "This study showed that the high expression of SAMHD1 in stage II colorectal cancer tissues was correlated with poor prognosis." (PMID 35978833, 2022). "The expression level of SAMHD1 tended to be associated with the 5-year OS (SAMHD1-high vs. SAMHD1-low; HR = 1.82; 95% CI, [0.94–3.56]; and P = 0.073) among patients with stage II and III colorectal cancer." (PMID 35978833, 2022). "Consistent with our TCGA database analysis, we have identified that some of colorectal cancer-relevant SAMHD1 mutants have lower expression levels than that of the wild-type SAMHD1." (PMID 33857133, 2021). "In conclusion, our research showed that SAMHD1 can effectively stratify patients with stage II colorectal cancer into subgroups with good and poor prognosis, thereby complementing the prognostic value of the MSI/MMR status that is used to evaluate the prognosis of these patients." (PMID 35978833, 2022). "SAMHD1-high expression could help in identifying patients with stage II colorectal cancer with poor prognosis and less benefit from adjuvant chemotherapy." (PMID 35978833, 2022). "Moreover, a previous study reported that SAMHD1 upregulation was found in the colorectal cancer tissue of the patients with advanced colorectal cancer compared to their normal counterparts." (PMID 35978833, 2022). "To test the relevance of the TRC-dependent R-loop regulatory function of SAMHD1 in cancer, we have examined whether colorectal cancer-relevant SAMHD1 mutants can regulate cellular TRCs." (PMID 33857133, 2021). "Moreover, we identified two colorectal cancer-relevant SAMHD1 mutants, which cannot restore the increased TRCs in SAMHD1-depleted cells." (PMID 33857133, 2021). "Using public colorectal cancer datasets for biomarker discovery, we illustrated that SAMHD1 had prognostic and predictive powers that could be helpful for patients with stage II colorectal cancer and had a predictive power in those with stage III colorectal cancer." (PMID 35978833, 2022). "Additionally, we compared and contrasted SAMHD1 expression according to KRAS mutation status, BRAF mutation status, tumor location, and defective DNA mismatch repair status, as they were frequently mutated genes or risk parameters in colorectal cancer." (PMID 35978833, 2022). "Hence, the expression level of SAMHD1 could be a prognostic biomarker for stage II colorectal cancer." (PMID 35978833, 2022). "This study is the first to demonstrate that SAMHD1 is a predictive biomarker for adjuvant chemotherapy in patients with stage II and III colorectal cancer." (PMID 35978833, 2022). "In recent years, SAMHD1 has been proposed as a prognostic marker mainly in different types of hematological cancers, but also to a lesser extent in different solid tumors such as NSCLC and colorectal cancer." (PMID 37667113, 2024). "Hence, SAMHD1 could complement MSI/MMR status as a molecular marker involved in the high-risk definition for patients with stage II colorectal cancer and help in making clinical decisions for adjuvant chemotherapy for patients with stages II and III colorectal cancer." (PMID 35978833, 2022).
colorectal cancer (continued). "SAMHD1 could complement MSI/MMR status as a promising molecular marker, leading to more accurate treatment decisions in patients with stage II colorectal cancer." (PMID 35978833, 2022). "Therefore, evaluation of the expression levels of SAMHD1 in patients with stages II and III colorectal cancer before adjuvant chemotherapy is warranted." (PMID 35978833, 2022). "We made similar observations in the murine colorectal cancer cell line CT26 upon SAMHD1 knockout (data not shown)." (PMID 32402273, 2020). "Thus, SAMHD1 may potentially be used as an easy and useful tool in clinical practice to develop more accurate treatment decisions for patients with stages II and III colorectal cancer." (PMID 35978833, 2022).